KIFC1 (kinesin family member C1)
Diseases named in the same sentence as KIFC1 in open-access papers (continued):
Sharing a sentence is not in itself a finding about the gene and the disease.
cancer (continued). "We analyzed RNA sequencing expression data of 9736 tumors and 8587 normal samples from The Cancer Genome Atlas (TCGA) and the Genotype-Tissue Expression (GTEx) projects for the expression profiles of centrosome clustering proteins KIFC1, AURKB, BIRC5, and CDCA8." (PMID 39335162, 2024). "However, as in cancer cells, it was also dependent on KIFC1, inhibition of which reduced centrosomal clustering and subsequent proplatelet formation." (PMID 38896608, 2024). "In addition, abnormal centrosome amplification, which was reported to be partially regulated by KIFC1, usually occurred in different cancers." (PMID 39349439, 2024). "In addition, KIFC1, an essential centrosome clustering molecule, was reported to be overexpressed in various cancers, especially EC." (PMID 39349439, 2024). "KIFC1 may be an actionable cancer-cell-specific target for the AR-low TNBC subpopulation and could aid in alleviating racial disparities in TNBC outcomes." (PMID 38003261, 2023). "Furthermore, studies have reported the involvement of KIFC1 in promoting the initiation and progression of various carcinomas." (PMID 38112634, 2023). "In the present study, the intersection analysis of the KIFC1-interacted proteins and the KIFC1-correlated genes identified two genes, ASPM and TUBB, as the potential important regulatory molecules that are associated with KIFC1 for cancer cell division." (PMID 35327439, 2022). "A combination of the small molecular inhibitors for KIFC1 and the immune checkpoint blocker(s) may be an effective option for overcoming the drug resistance in cancers." (PMID 35327439, 2022). "In conclusion, the present pan-cancer analyses of KIFC1 elucidates that the KIFC1 expression was correlated with the oncogenic signature gene sets, the MDSC infiltration, the ImmunoScore, the immune checkpoints, the MSI, the TMB, and the clinical prognosis across multiple tumors." (PMID 35327439, 2022). "Inhibition of this phosphorylation reverted both phenotypes, therefore there is ample evidence suggesting that the targeted inhibition of KIFC1 could be a treatment option in cancers with amplified centrosomes." (PMID 35053604, 2022). "Under KIFC1 and cyclin/CDK inhibitors, this caused eradication of the cancer under the ET hypothesis." (PMID 35962062, 2022). "In this study, we showed that KIFC1 is a potential marker for clinical cancer recurrence." (PMID 33397932, 2021). "Additionally, thirty-three TCGA datasets of other cancer types, when analyzed simultaneously, demonstrated a trend with higher KIFC1 expression and lower recurrence-free survival." (PMID 33760984, 2021). "This could indicate that higher ploidy cancers need higher levels of centrosome clustering mediated by KIFC1." (PMID 33760984, 2021). "Next, we looked at KIFC1 expression across multiple cancer types." (PMID 33760984, 2021). "KIFC1 allows cancer cells with multiple centrosomes to survive cell division." (PMID 33760984, 2021). "Kinesin family member C1 (KIFC1/HSET), a microtubule binding protein of the kinesin-14 family, prevents the death of cells with centrosome amplification (CA), which is a hallmark of cancer." (PMID 34945833, 2021). "This information leads us to hypothesize if KIFC1 could be inhibited effectively in combination with other treatment options it would lead to increased cancer cell lethality." (PMID 33760984, 2021). "KIFC1 expression was increased in high T stage cancer in the study GSE120736." (PMID 34768355, 2021). "We unveil that such differences arise because, while LE retrograde transport depends on the dynein microtubule (MT) motor only, the one of EEs requires the cooperative antagonism of dynein and kinesin‐14 KIFC1, a MT minus end‐directed motor involved in cancer progression." (PMID 33215754, 2020). "These new data have again brought KIFC1 to the fore as a candidate cancer-specific target." (PMID 31506331, 2019). "KIFC1 is essential for mitosis not only in normal cells, but also in cancer cells." (PMID 31895691, 2019).
cancer (continued). "In addition, KIFC1 is reported with a critical role in centrosome clustering in various cancer cells such as hepatocellular carcinoma and it has been suggested as a potential prognostic biomarker and therapeutic target for cancer treatment." (PMID 31895691, 2019). "KIFC1 presents upregulated in various cancer cells and is related to cancer progression." (PMID 31895691, 2019). "KIFC1 is essential for bipolar spindle formation, and KIFC1 knockdown induced multipolar spindle mitotic defects in cancer cells containing extra centrosomes and induced cancer cell death." (PMID 31340839, 2019). "In cancer cells, KIFC1 proteins are disrupted by a higher level of Ran and form multipolar spindles with numerous clustered centrosomes, thus it’s considered as one of the targeted proteins of cancer cells for clinical usage." (PMID 31127080, 2019). "Therefore, targeting centrosome-amplified cells by KIFC1 inhibition would be expected to have effects in many cancer types." (PMID 29535384, 2018). "In contrast to its low expression in other cells, KIFC1 shows high expression in many cancer cells." (PMID 29123223, 2017). "Because of its elevated expression in different cancer cells and the demonstrated dependence on KIFC1 for viability of these cells, together with the relative insensitivity of normal cells to its depletion, KIFC1 has been the target of several small molecule inhibitor screens." (PMID 29123223, 2017). "Therefore, KIFC1 is considered to be a new-generation chemotherapy target for cancer, as it plays important roles in cancer cell division, which usually possess more than two centrosomes, but is not as important in normal cells." (PMID 28977870, 2017). "Human kinesin-14 KIFC1 is unique in that cancer cells with amplified centrosomes are dependent on the motor for viable division because of its ability to cluster centrosomes and form bipolar spindles, but it is not required for division in almost all normal cells." (PMID 29123223, 2017). "This strong relationship of KIFC1 with HGSOC suggests that KIFC1 may be directly involved in tumor development and in driving aggressiveness by allowing the cancer/poorly differentiated cells to escape mitotic catastrophe and thrive." (PMID 26992853, 2016). "• KIFC1 (kinesin family member C1) is a minus end-directed motor protein of the kinesin-14 family, which is involved in the process of centrosome clustering in cancer cells that display amplified centrosomes." (PMID 26527623, 2016). "It is possible that once metastasis commences, high KIFC1 levels in the metastatic clones provides little further survival advantage for the cancer cells; alternatively, once metastasis occurs, the survival difference between KIFC1-high and KIFC1-low patients is no longer so marked." (PMID 26992853, 2016). "HSET/KifC1, a minus end-directed motor protein that promotes microtubule cross-linking, sliding, bundling and spindle pole focusing, has been recently identified as an essential mediator of supernumerary centrosome clustering in cancer cells." (PMID 25788277, 2015). "KIFC1 is a kinesin involved in various cellular processes such as mitotic spindle assembly, centrosome clustering, and vesicle transport in cancer cells." (PMID 25028599, 2014). "However, KIFC1 has been established as a cancer-specific dependency in TNBC." (PMID 39789388, 2025). "Thus, KIFC1 was regarded as a promising chemotherapy target for cancer treatment." (PMID 39349439, 2024). "Furthermore, the KEGG pathway and GO enrichment analyses indicated that KIFC1 may participate in carcinogenesis by influencing key biological processes such as “cell cycle” and “DNA replication” in cancer cells." (PMID 38112634, 2023). "However, there was considerable variation in KIFC1 expression levels within the cancer tissues." (PMID 37955677, 2023). "Hence, KIFC1 inhibition may be a promising anti-cancer strategy for QNBC women of West African ancestry." (PMID 36139643, 2022).
cancer (continued). "Thus, a pan-cancer analysis of KIFC1 may provide new insights into the molecular mechanisms for tumor occurrence, recurrence, and immunotherapy." (PMID 35327439, 2022). "This study identified KIFC1 as a prognostic tumor recurrence marker, and revealed that tumors can acquire therapeutic resistance and recurrence via triggering centrosome clustering under DNA damage stresses, suggesting that blocking KIFC1 phosphorylation may open a new vista for cancer therapy." (PMID 33397932, 2021). "Thereby, the hypothesis by which KIFC1 overexpression may promote cancer growth and metastatic dissemination via the alteration of the early endosomal routes may be a further development for future cancer studies." (PMID 33215754, 2020). "Furthermore, KIFC1 motor plays important roles in cancer cell division, which usually possesses more than two centrosomes and thus measured to be a new-generation chemotherapy target for cancer." (PMID 32842864, 2020). "Furthermore, KIFC1 is widely expressed in cancer cells and may be essential for the bi-multipolar mitotic division of cancer cells but is dispensable in ordinary somatic cells, which qualifies KIFC1 as an excellent target in cancer therapy." (PMID 30991738, 2019). "However, that KIFC1 also plays roles in other specific cell types complicates the question of whether it is a promising chemotherapy target for cancer treatment." (PMID 27102297, 2016). "Thus, KIFC1 overexpression not only protects cancer cells from undergoing mitotic catastrope but also endows them with low-grade aneuploidy, as a form of genomic instability, and high levels of survival signaling that together facilitate tumor evolution and disease progression." (PMID 26992853, 2016). "Moreover, KIFC1 is also found to initiatively drive tumor malignancy and metastasis by stabilizing a certain degree of genetic instability, delaying cell cycle and protecting cancer cell surviving signals." (PMID 27102297, 2016). "Since KIFC1 has been shown to predict non-small cell lung cancer metastasis to the brain, we were inquisitive to examine its usefulness as a risk predictor and/or negative prognosticator in other aggressive cancer types which harbor amplified centrosomes." (PMID 25028599, 2014). "Through in silico and in vitro analyses, as well as IHC of clinical samples, we found that KIFC1 is overexpressed and that centrosome amplification occurs more frequently in SCLC compared with normal tissues and other cancer types." (PMID 41948931, 2026). "In the PJ34-treated cancer cells, the unclustering of NuMA in spindle poles was accompanied by the interference of PJ34 with NuMA binding to α-tubulin and to kinesins HSET/KifC1 and Kif18A that interact with αβ-tubulin." (PMID 40681496, 2025). "SR31527 inhibits spindle formation in cancer cells, while PJ34 suppresses KIFC1 expression, thereby reducing cell proliferation." (PMID 41477589, 2025). "A variety of genetic and small-molecule inhibitor studies have converged on kinesin family member C1 (KIFC1; also known as HSET) as a promising target due to its essential role in centrosome clustering in cancer cells." (PMID 38896608, 2024). "The analysis revealed a significant correlation between KIFC1 expression and MYC targets, E2F targets, Mitotic spindle, G2M checkpoint, and MTORC1 signaling in the majority of cancer types." (PMID 38112634, 2023). "The results demonstrated that the expression of KIFC1 was significantly positively related to MHC molecules, chemokines, immunostimulators, and immunoinhibitors in several types of cancer, especially in THCA." (PMID 38112634, 2023).
cancer (continued). "To investigate the expression and function of KIFC1 in ESCC, we conducted immunohistochemical staining on 30 pairs of para-carcinoma tissue and cancerous tissues, revealing a significant increase in KIFC1 expression in ESCC tissues." (PMID 37955677, 2023). "Thus, KIFC1-induced centrosome amplification may lead to a delay of the mitotic exit in cancer." (PMID 35327439, 2022). "In fact, KIFC1 inhibitors (e.g., AZ82, CW069, and SR31527) have been identified and being studied for potential therapy of different forms of cancers." (PMID 35327439, 2022). "Kinesin family member C1 (KIFC1), a minus end-directed motor protein, is a novel Kinesin involved in the clustering of excess centrosomes found in cancer cells." (PMID 33760984, 2021). "Knockdown of KIFC1 increased expression of E-cadherin and decreased expression of N-cadherin, Snail, and ZEB1 in cancer cells." (PMID 34945833, 2021). "Furthermore, KIFC1 inhibition, which selectively targets cells harboring CA, has been shown to be an effective minimally cytotoxic anti-cancer strategy in preclinical studies." (PMID 34945833, 2021). "Loss of E-Cadherin, whether experimentally induced or occurring in cancer cells that have undergone epithelial to mesenchymal transition, increases cortical contractility, limiting the movements of supernumerary centrosomes, which in turn allows them to be clustered by a KIFC1-dependent mechanism." (PMID 31506331, 2019). "The cytotoxic activity of the phenanthrenes in a variety of human cancer cells is attributed by these findings to post translational modifications of NuMA and kinesins HSET/kifC1 and kif18A." (PMID 28209915, 2017). "In cancer cells, the human kinesin-14 HSET/KIFC1 is needed for clustering multiple centrosomes, a process crucial for cancer cell proliferation and survival." (PMID 28051135, 2017). "A centrosome clustering molecule, KIFC1 (also known as HSET), a minus end-directed motor protein of the kinesin-14 family, is essential for the viability of extra centrosome-bearing cancer cells." (PMID 25028599, 2014). "Given that normal somatic cells do not rely on KIFC1 for spindle organization, its targeted inhibition presents a promising strategy for selectively disrupting cancer cell." (PMID 40471955, 2025). "As our data suggest that OTUD6B may also be required to cluster supernumerary centrosomes in cancer cells, we next examined how OTUD6B expression relates to KIFC1 expression, centrosome amplification and patient outcomes." (PMID 39789388, 2025). "Overall, these data suggest that cancer cells with centrosome amplification depend upon the catalytic activity of OTUD6B to safely execute cell division, at least in part through the role of OTUD6B in protecting KIFC1, which facilitates centrosome clustering." (PMID 39789388, 2025). "TMC-52A has been identified as a cysteine protease inhibitor, while Muscimol functions as a GABAA receptor agonist, however, the remaining compounds have no previous biological documentation concerning cancer or KIFC1." (PMID 41477589, 2025). "Our analyses of TCGA and GTex tumor data and matched normal samples from TCGA and GTex datasets using the Gene Expression Profiling Interactive Analysis (GEPIA) tool showed that KIFC1, AURKB, BIRC5, and CDCA8 are all significantly overexpressed in many different cancer types." (PMID 39335162, 2024). "Conversely, KIFC1 showed a negative association with the infiltration levels of NK T cells and HSCs, particularly in BLCA, LUAD, and SARC among the TCGA cancers." (PMID 38112634, 2023). "KIFC1 has been identified as highly expressed in several types of cancer, although its prognostic value is inconsistent, and no research has been conducted specifically on its effect on ESCC." (PMID 37955677, 2023). "In the cancer tissues, the expression level of KIFC1 was significantly higher than that in adjacent non-tumor tissues, though negative expression samples were also present." (PMID 37955677, 2023).
cancer (continued). "In cancer tissues, the proportion of KIFC1-positive cells increased, although not all cells exhibited positive staining." (PMID 37955677, 2023). "The findings revealed a positive correlation between KIFC1 expression and the infiltration levels of CD4+ T cells, CD8+ T cells, myeloid-derived suppressor cells (MDSCs), T follicular helper cells (Tfh), and macrophages in the majority of TCGA cancers." (PMID 38112634, 2023). "Although KIFC1 was not a hit in the human cancer screen, many subsequent studies have confirmed its contribution to centrosome clustering in human tumor cells." (PMID 35053604, 2022). "Thus, inhibition of KIFC1 is a promising strategy to prevent CIN and cellular invasion in cancer therapy." (PMID 33397932, 2021). "KIFC1, while not expressed in somatic cells, is widely expressed in cancers such as ovarian, breast, bladder, lung, kidney, and we report here, prostate." (PMID 33760984, 2021). "KIFC1 is non-essential for normal somatic cells but necessary for the proper division of cancer cells with excess centrosomes." (PMID 33760984, 2021). "KIFC1 is normally a nonessential kinesin motor but plays important roles in cancer cells with extra centrosomes." (PMID 31340839, 2019). "Notably, a drug targeting KIFC1 has been already developed (AZ82) and tested in cancer cells, and this drug was demonstrated to specifically affect the survival of cancer cells with amplified centrosomes." (PMID 26527623, 2016). "Given the excellent promise of KIFC1 as a therapeutic target, its role as a negative prognosticator merits investigation in cancers with amplified centrosomes." (PMID 25028599, 2014). "KIFC1 is a non-essential gene for normal breast cells; therefore, KIFC1 could serve as a cancer-selective therapeutic target." (PMID 40448099, 2025). "It was notice that KIFC1 is non-essential in normal cells but is crucial for the survival of tumor cells with amplified centrosomes, rendering it an attractive and selective target for cancer treatments." (PMID 41477589, 2025). "Kinesins HSET/kifC1 and kif18A have already been examined for their possible role in cancer therapy, while to the best of our knowledge, NuMA clustering in the spindle poles has not been examined before as a target for cancer cells’ eradication." (PMID 40681496, 2025). "Additionally, KIFC1 is non-essential for healthy cells with 2 centrosomes but indispensable for proper cell division of cancer cells with supernumerary centrosomes." (PMID 36139643, 2022). "The fact that KIFC1 plays an essential role in the centrosome amplification in cancer cells, and not in normal diploid cell division, suggests that KIFC1 may be an attractive therapeutic target for human cancers." (PMID 35327439, 2022). "However, it is unclear whether the interactions among KIFC1, ASPM, and TUBB have synergistic effects on the progression of cancer." (PMID 35327439, 2022). "Thus, KIFC1 inhibitors can selectively kill cancer cells burdened with extra centrosomes unlike standard chemotherapies." (PMID 36139643, 2022). "We specifically looked at therapies that target three key aspects in the life cycle of cancer cells: formation of the PACC state (with cyclin/CDK inhibitors), the stable PACC state (with metabolism modulation), and depolyploidization from the PACC state (with KIFC1 inhibitors)." (PMID 35962062, 2022). "However, if the KIFC1 inhibitor is given 50 time steps after the administration of chemotherapy, the cancer population is not driven to extinction." (PMID 35962062, 2022). "Interestingly, KIFC1 and TACC3 are also required for acentrosomal spindle assembly in multiple organisms, suggesting that cancer cells may be dependent on these meiotic mechanisms to form bipolar spindles when the centrosome complement of the cell is abnormal." (PMID 31506331, 2019). "KIFC1 may be essential for cancer cell division but may not be essential for cell migration of HeLa cells." (PMID 28977870, 2017).